TMEM127 (transmembrane protein 127)
Description:
Controls cell proliferation acting as a negative regulator of TOR signaling pathway mediated by mTORC1. May act as a tumor suppressor.
Synonyms: FLJ20507; FLJ22257
Tractability: Antibody: UniProt places it where antibodies can reach, with high confidence; its Gene Ontology location is reachable by antibodies, with high confidence; UniProt predicts a signal peptide or a membrane-spanning region. PROTAC: ubiquitination databases record sites on it; its protein half-life has been measured.
Gene: Protein-coding gene on chromosome 2 (96,248,500 to 96,266,047, reverse strand). Ensembl gene ENSG00000135956.
Subcellular location: Cell membrane; Cytoplasm
Gene Ontology:
Molecular function: small GTPase binding
Biological process: negative regulation of cell population proliferation; negative regulation of TOR signaling; regulation of TOR signaling
Cellular component: cytoplasm; early endosome; plasma membrane; membrane
Genetic constraint (gnomAD): Loss-of-function variants: 21 observed, 18.99 expected, observed/expected ratio (o/e) 1.11, 90% interval 0.78 to 1.59. The upper end of that interval is the gene's LOEUF score, 1.59, which puts it in group 6 of 6, group 1 being the genes least tolerant of losing a copy. Missense variants: 303 observed, 311.31 expected, observed/expected ratio (o/e) 0.97, 90% interval 0.88 to 1.07. Synonymous variants: 150 observed, 136.26 expected, observed/expected ratio (o/e) 1.1, 90% interval 0.96 to 1.26.
Gene-disease validity (ClinGen):
ClinGen rates the evidence that TMEM127 causes each of these diseases.
hereditary pheochromocytoma-paraganglioma (autosomal dominant): Definitive. Neoplasm predisposition characterized by an increased risk of paragangliomas (tumors that arise from neuroendocrine tissues distributed along the paravertebral axis from the base of the skull to the pelvis) and pheochromocytomas (paragangliomas that are confined to the adrenal medulla).
Homologues: Orthologues: chimpanzee TMEM127 (100% identical), dog TMEM127 (100% identical), macaque TMEM127 (100% identical), pig TMEM127 (100% identical), guinea pig TMEM127 (99% identical), rabbit TMEM127 (99% identical), rat Tmem127 (99% identical), mouse Tmem127 (99% identical), tropical clawed frog tmem127 (86% identical), zebrafish tmem127 (84% identical).
Diseases named in the same sentence as TMEM127 in open-access papers:
TMEM127 is named in the same sentence as 47 diseases in open-access papers, as found by Europe PMC text mining. Sharing a sentence is not in itself a finding about the gene and the disease. The quoted sentences say what the papers report.
pheochromocytoma (33 papers, 2013 to 2026). "As a tumor suppressor, germline mutations in TMEM127 are associated with hereditary pheochromocytomas and paragangliomas." (PMID 41357074, 2025). "TMEM127 has been reported to be closely associated with pheochromocytoma, paraganglioma and renal cancer." (PMID 35941331, 2022). "In humans, germline loss-of-function TMEM127 mutations confer susceptibility to neuroendocrine, sympathetic nervous system-derived tumors (pheochromocytomas) and renal cancers." (PMID 31624249, 2019). "VHL, RET, NF1, SDHB, and SDHD are major susceptibility genes, accounting for 90% of familial pheochromocytomas/paragangliomas, whereas TMEM127, SDHA, SDHC, SDHAF2, and MAX are minor susceptibility genes responsible for 10% of these tumors." (PMID 30456751, 2018). "Germline missense mutations in the TMEM127 gene or mutations leading to truncated forms of this protein were detected among 103 patients with pheochromocytomas, wherein approximately 30% of hereditary tumors and 3% of sporadic tumors carried the mutant gene." (PMID 28187001, 2017). "The transcription profile of TMEM127-mutant pheochromocytomas was found to be similar to that of tumors with mutations in the RET and NF1 genes." (PMID 28187001, 2017). "The prevalence of TMEM127 mutations in patients with paraganglioma/pheochromocytoma varies between 0.9 and 2%." (PMID 24899893, 2014). "Loss of function mutations in TMEM127 are notably associated with pheochromocytoma." (PMID 39000254, 2024). "The TMEM127 gene, on the other hand, is a gene that acts mainly as a tumor suppressor; it encodes a transmembrane protein whose function remains elusive, and is frequently found mutated in pheochromocytomas and, to a lesser extent, in renal cancers." (PMID 39336996, 2024). "KIF1B is a rare reason for pheochromocytoma and TMEM127 is a susceptibility gene for PGL/PCC." (PMID 33777662, 2021). "Mutations in TMEM127 confer susceptibility to pheochromocytoma, a tumour of the adrenal gland." (PMID 32526160, 2020). "The TMEM127 gene was recently identified as a new phaeochromocytoma susceptibility gene." (PMID 31781416, 2019). "TMEM127 is a tumour suppressor gene (four exons, chromosome 2q11) linked with mTOR (mammalian target of rapamycin) kinase pathway which has recently been associated with the development of phaeochromocytoma." (PMID 29166454, 2017). "Recent advances in molecular analysis and familiar screening identified the pivotal role of new susceptibility genes in the pathogenesis of pheochromocytoma, such as SDHA, TMEM127, MAX, and SDHAF2." (PMID 39336996, 2024). "Pheochromocytomas carrying TMEM127 mutations exhibit elevated levels of LAMTOR proteins, while generally, a loss of TMEM127 drives RET-mediated tumor transformation, deregulating membrane dynamics." (PMID 39336996, 2024). "Cluster 2 PPGLs are built-up mostly by pheochromocytomas driven by variants in genes regulating kinase-driven pathways, including NF1, KIF1B, MAX, RET, TMEM127 and H-RAS." (PMID 35205664, 2022). "SDHA, SDHAF2, SDHB, SDHC, SDHD, MAX, and TMEM127 genes are offered to be analyzed for the diagnosis of paraganglioma/pheochromocytoma (PGL/PCC) syndromes." (PMID 33777662, 2021). "This case also supports the presence of a predominant adrenaline secreting pattern in TMEM127-positive tumours, as well as the need to consider multigene panel testing in patients with bilateral phaeochromocytomas." (PMID 31781416, 2019). "An analysis of transcription profiles showed the expression of mutant TMEM127 forms to be reduced more that 4-fold in pheochromocytomas as compared to tumors with wild-type TMEM127." (PMID 28187001, 2017). "More recently, the TMEM127, MAX, HIF2A, EGLN1, KIF1B, and H-RAS complete the list of susceptibility genes implicated in the development of paragangliomas/pheochromocytomas." (PMID 24899893, 2014).
pheochromocytoma (continued). "TMEM127 is a component of the ubiquitin system; its mutation causes RET stabilization, and this mechanism was discovered to be implicated in the tumorigenesis of pheochromocytoma." (PMID 39000254, 2024). "Germline VHL, SDHx and FH mutations may predispose to phaeochromocytoma/paraganglioma and RCC, and on rare occasions renal tumours have been reported in association with mutations in the phaeochromocytoma genes TMEM127 and MAX." (PMID 29680948, 2018). "We present a woman with the pathogenic variant c.86delG (p.Arg29Leufs∗52) in the TMEM127 gene, which has not been previously reported, associated to a bilateral phaeochromocytoma, with an uncommon initial clinical presentation and a biochemical profile that is distinctly adrenergic." (PMID 31781416, 2019). "Furthermore, the examination of 990 patients with paragangliomas/pheochromocytomas identified mutations in the TMEM127 gene in 2% of these, although none exhibited paragangliomas." (PMID 28187001, 2017). "Additional support for the relationship between TMEM127 and mTOR may be surmised from the elevated phosphorylation of mTOR targets both in cell lines lacking TMEM127 and in human pheochromocytomas with mutations in this gene." (PMID 28187001, 2017). "In a study of 972 cases from the European-American-Asian Pheochromocytoma and Paraganglioma Registry without mutations in the common PPGL genes, 58 had mutations in less commonly mutated genes (SDHA, TMEM127, SDHAF2) including 8 cases of PCC with MAX mutations." (PMID 31666924, 2019).
paraganglioma (21 papers, 2013 to 2026). A benign or malignant neoplasm arising from paraganglia located along the sympathetic or parasympathetic nerves. "Recently, other genes (TMEM127, MAX, HIF2A, EGLN1, KIF1B, H-RAS) have been added to the group of susceptibility genes involved in the development of paragangliomas/PHEO." (PMID 26084817, 2015).
renal cell carcinoma (4 papers, 2017 to 2025). "We report a case of MAX-associated renal cell carcinoma and confirm the role of TMEM127 mutations with renal cell carcinoma predisposition." (PMID 28973655, 2017). "TMEM127 functions are poorly understood but it has been suggested to facilitate endosomal transition and cargo trafficking and has been shown to modulate endolysosomal function in renal cell carcinomas." (PMID 38687678, 2024). "Interestingly, TMEM127 mutations have also been identified as drivers in other cancers, notably renal cell carcinoma, where RET is not highly expressed." (PMID 38687678, 2024).
neurofibromatosis (3 papers, 2015 to 2022). A hereditary neoplastic syndrome in which tumors grow in the nervous system. "Two nonsyndromic patients (cases 1 and 2) were negative to germline mutations in genes VHL, SDHB, SDHC, SDHD, SDHAF2, TMEM127, and MAX, while the third case (case 3) had clinical diagnosis of neurofibromatosis syndrome." (PMID 36187102, 2022).
neurofibromatosis type 1 (3 papers, 2014 to 2024). A clinically heterogeneous, neurocutaneous genetic disorder characterized by cafe-au-lait spots, iris Lisch nodules, axillary and inguinal freckling, and multiple neurofibromas. "Since then, at least 20 susceptibility genes have been detected to have germline mutations, such as NF1 (neurofibromatosis type 1), TMEM127 (transmembrane protein 127), FH (fumarate hydratase), VHL (Von Hippel-Lindau), and others." (PMID 35627249, 2022).
acute myeloid leukemia (2 papers, 2024 to 2025). Acute myeloid leukemia (AML) is a group of neoplasms arising from precursor cells committed to the myeloid cell-line differentiation. "In acute myeloid leukemia (AML), the sushi domain containing 6 (SUSD6) interacts with transmembrane protein 127 (TMEM127) and MHC-I, recruiting the E3 ubiquitin ligase WWP2." (PMID 39223632, 2024). "Interestingly, both TMEM127 and WWP2 were recently shown to deplete surface MHCI in acute myeloid leukemia (AML) cells." (PMID 41135677, 2025).
fatty liver disease (2 papers, 2019 to 2025). A reversible condition wherein large vacuoles of triglyceride fat accumulate in liver cells via the process of steatosis. "Additionally, TMEM127 has been implicated in metabolic disorders such as insulin resistance and fatty liver disease, with studies demonstrating a strong correlation between its expression levels and insulin sensitivity." (PMID 41357074, 2025). "Both human and mouse liver TMEM127 expression correlate with states of insulin resistance and advanced hepatic steatosis, suggesting that TMEM127 may be a relevant target for treating insulin resistance and its hepatic complications." (PMID 31624249, 2019). "Finally, and of translational relevance, we found that hepatic TMEM127 expression correlates with fatty liver disease and insulin-resistant states both in mice and in humans." (PMID 31624249, 2019).
Insulin resistance (2 papers, 2019 to 2025). Increased resistance towards insulin, that is, diminished effectiveness of insulin in reducing blood glucose levels. "Loss of Tmem127 enhances insulin sensitivity and protects from diet-induced insulin resistance likely due to reduced hepatic gluconeogenesis and increased glucose clearance in fat tissue, although other mechanisms may also be involved." (PMID 31624249, 2019). "We next examined hepatic Tmem127 mRNA in two well-known genetic models of diabetes, obesity, and insulin resistance, in which the metabolic disruption exists even under a regular diet, the Db/Db and Ob/Ob mice." (PMID 31624249, 2019). "Our results suggest that besides tumor suppression activities, TMEM127 is a nutrient-sensing component of glucose/lipid homeostasis and may be a target in insulin resistance." (PMID 31624249, 2019). "This profile suggests that Tmem127 expression might contribute to the age-related increase in insulin resistance." (PMID 31624249, 2019). "Importantly, human liver TMEM127 expression correlates with steatohepatitis and insulin resistance." (PMID 31624249, 2019). "Hence, we examined Tmem127 expression in several mouse models of insulin resistance." (PMID 31624249, 2019).
metastatic disease (2 papers, 2022 to 2026). "Three tumors were from patients who developed metastatic disease (E205, PC, EPAS1; E206, PC, EPAS1; E235, PC, MAML3-fusion), and two tumors had locally invasive features (E007, TMEM127; E025, AT-PG, SDHA)." (PMID 36271074, 2022). "In our analyses of risk rate not adjusted for time, we found a significantly increased risk of metastatic disease in patients with pathogenic germline variants in SDHA, SDHB, SDHC, TMEM127, MAX, and FH compared to those with no identified pathogenic variant." (PMID 41183483, 2026).
multiple endocrine neoplasia type 2 (2 papers, 2014 to 2016). Multiple endocrine neoplasia type 2 (MEN2) is a multiple endocrine neoplasia, a polyglandular cancer syndrome characterized by the occurrence of medullary thyroid carcinoma (MTC), pheochromocytoma (PCC), in one variant, primary hyperparathyroidism (PHPT). "The kinase signalling subgroup, includes characteristic mutations in REarranged during Transfection (RET) in Multiple Endocrine Neoplasia type 2 (MEN2), Neurofibromatosis type 1 (NF1), transmembrane protein 127 (TMEM127), MYC associated factor X (MAX), EGLN1 (PHD2), KIF1 and IDH1." (PMID 27535829, 2016).
neuroendocrine tumors (2 papers, 2020 to 2022). "While models for genes of cluster 2 PPGL (RET, NF1, and TMEM127) have been studied since 1992, these models are suboptimal as they are generally associated with development of additional unrelated non-neuroendocrine tumors." (PMID 36428741, 2022).
pituitary adenoma (2 papers, 2015 to 2018). "Known pheo/PGL genes (SDHA-D, SDHAF2, RET, VHL, TMEM127, MAX, FH) and pituitary adenoma genes (MEN1, AIP, CDKN1B) were sequenced using next generation or Sanger sequencing." (PMID 25494863, 2015).
adrenal pheochromocytoma (1 paper, 2020). "MAX variants are almost exclusively identified in patients with adrenal pheochromocytoma that are frequently bilateral, while TMEM127 variant carriers most commonly present with single adrenal pheochromocytoma, and occasionally multiple head and neck or thoraco-abdominal PGLs." (PMID 33308260, 2020).
cholera (1 paper, 2022). "The region with the strongest signal of selection, located on chromosome 2 and encompassing five genes (NRNP200, CIAO1, ITPRIPL1, NCAPH, and TMEM127) was also the region showing the strongest association with cholera, with the top associated SNPs located between the genes NRNP200 and ITPRIPL1." (PMID 35925921, 2022).
gastric cancer (1 paper, 2020). A primary or metastatic malignant neoplasm involving the stomach. "Therefore, we suspect that METTL3/miR-17-92 cluster activates mTOR pathways by targeting PTEN and TMEM127 in gastric cancer progression." (PMID 33037176, 2020). "So far, the function of TMEM127 in gastric cancer and its association with the miR-17-92 cluster have not been reported." (PMID 33037176, 2020). "In conclusion, METTL3/m6A promotes gastric cancer growth and metastasis by facilitating pri-miR-17-92 processing into the oncogenic miRNA cluster and activating the AKT/mTOR pathway by targeting PTEN and TMEM127, which could be targeted by everolimus." (PMID 33037176, 2020).
hyperthyroidism (1 paper, 2025). Overactivity of the thyroid gland resulting in overproduction of thyroid hormone and increased metabolic rate. "Two machine learning algorithms, LASSO and RF, were employed to identify CXCL16 and TMEM127 as biomarkers significantly associated with both hyperthyroidism and AF." (PMID 41357074, 2025). "The two genes demonstrated good diagnostic efficacy in the hyperthyroidism validation set GSE276271 (AUC: TMEM127, 0.636; CXCL16, 0.591) and in the AF validation set GSE2240 (AUC: TMEM127, 0.745; CXCL16, 0.720)." (PMID 41357074, 2025). "CXCL16 and TMEM127 are promising biomarkers, offering insights into the shared pathogenesis of hyperthyroidism and AF." (PMID 41357074, 2025). "The results demonstrated that the gene expression levels of CXCL16 and TMEM127 were significantly upregulated in both the hyperthyroidism and AF groups compared to the control group." (PMID 41357074, 2025). "RT–qPCR analysis demonstrated that CXCL16 and TMEM127 expression levels were significantly elevated in both the hyperthyroidism and AF groups compared to the control group, aligning with the findings from our prior bioinformatics analysis." (PMID 41357074, 2025). "RT–qPCR analysis revealed that the expression levels of CXCL16 and TMEM127 were significantly elevated in both the hyperthyroidism and AF groups compared to the control group, corroborating the results of our bioinformatics analysis." (PMID 41357074, 2025). "Although a direct link between TMEM127 and AF or hyperthyroidism has not yet been established, its crucial role in key signaling pathways and cellular regulation suggests potential relevance." (PMID 41357074, 2025). "In the hyperthyroidism validation dataset, CXCL16 and TMEM127 achieved area under the curve (AUC) values of 0.636 and 0.591, respectively, while in the AF validation dataset, the values were 0.745 and 0.720, demonstrating their diagnostic potential for both diseases." (PMID 41357074, 2025).
liver disease (1 paper, 2019). "We found that hepatic TMEM127 expression, measured by RNAseq, was higher in patients with liver disease relative to controls." (PMID 31624249, 2019).
neuroblastoma (1 paper, 2024). Neuroblastoma (NB) is the most common solid, extracranial childhood tumor. "Using a CRISPR TMEM127-KO in the neuroblastoma cell line SH-SY5Y, we noted significantly increased levels of endogenously expressed RET protein, which appeared primarily as the higher molecular weight fully glycosylated form found at the cell surface." (PMID 38687678, 2024). "We therefore generated a CRISPR-Cas9 TMEM127-knockout (KO) and control (Mock-KO) in human neuroblastoma cell line SH-SY5Y, which endogenously expresses RET and TMEM127, to explore the effects of TMEM127 loss of function on RET localization and functions." (PMID 38687678, 2024).
Obesity (1 paper, 2019). Accumulation of substantial excess body fat. "We next asked whether Tmem127 deficiency would confer resistance to diet-induced obesity and its accompanying metabolic disruptions." (PMID 31624249, 2019).
osteosarcoma (1 paper, 2022). A usually aggressive malignant bone-forming mesenchymal neoplasm, predominantly affecting adolescents and young adults. "Functionally, we further proved that miR-23b-5p is a promoter of OS cell proliferation, migration and invasion by targeting TMEM127, which provides a potential diagnostic marker and therapeutic target for the treatment of osteosarcoma." (PMID 35941331, 2022). "Wound healing tests and transwell experiments showed that lower levels of TMEM127 promoted osteosarcoma cell metastasis and invasion." (PMID 35941331, 2022). "We found that mir-23b-5p promotes the progression of osteosarcoma by regulating TMEM127." (PMID 35941331, 2022).
Salmonella Infections (1 paper, 2025). Infections with bacteria of the genus SALMONELLA. "We first analysed the contribution of each PY motif and the cytoplasmic regions of TMEM127 to SteD-mediated reduction of surface levels of mMHCII during Salmonella infection by scanning mutagenesis." (PMID 41135677, 2025).